ENSG00000282804 (novel protein)
Gene: Protein-coding gene on chromosome 6 (24,797,373 to 24,809,798, reverse strand). Ensembl gene ENSG00000282804.
Genetic constraint (gnomAD): Loss-of-function variants: 4 observed, 4.04 expected, observed/expected ratio (o/e) 0.99, 90% interval 0.47 to 1.83. That is too few expected variants to judge how well the gene tolerates losing a copy. Missense variants: 42 observed, 48.12 expected, observed/expected ratio (o/e) 0.87, 90% interval 0.68 to 1.13. Synonymous variants: 17 observed, 16.85 expected, observed/expected ratio (o/e) 1.01, 90% interval 0.69 to 1.51.